STAT3 (signal transducer and activator of transcription 3)
Diseases named in the same sentence as STAT3 in open-access papers (continued):
Sharing a sentence is not in itself a finding about the gene and the disease.
staphylococcal pneumonia (1 paper, 2024). Pneumonia caused by infections with bacteria of the genus staphylococcus, usually with staphylococcus aureus. "The strong effect of STAT3 deficiency on the mainly proinflammatory response likely contributes to tissue damage and delayed healing in staphylococcal pneumonia in individuals with STAT3-deficient HIES." (PMID 37982695, 2024). "Because macrophages are involved in both pathogen defense and inflammation, we investigated the impact of murine myeloid STAT3 deficiency on the macrophage phenotype in vitro and on pathogen clearance and inflammation during murine staphylococcal pneumonia." (PMID 37982695, 2024). "Together with the observed enhanced MMP9 release as well as other epithelial factors involved in extracellular matrix remodeling, this may affect healing in staphylococcal pneumonia in STAT3 deficiency." (PMID 37982695, 2024). "Thus, our findings not only may play a role in the observed phenotype in STAT3-deficient patients with HIES but also could be further explored as a rationale in diagnostic testing for staphylococcal pneumonia." (PMID 37982695, 2024). "In our nonlethal staphylococcal pneumonia model, the lack of myeloid STAT3 did not affect pathogen clearance and overall cell counts." (PMID 37982695, 2024).
synovial sarcoma (1 paper, 2014). "A more recent study showed treatment of synovial sarcoma cells with dasatinib also led to apoptosis, decreased proliferation, and was associated with reduced phosphorylation of IGF-1R, AKT and Stat3." (PMID 25236161, 2014).
systemic vasculitis (1 paper, 2024). "In rare cases, STAT3 GOF syndrome may also present with systemic vasculitis, including cerebral and pulmonary vasculopathy, which had also been suspected from radiological imaging of our patients, although not ascertained." (PMID 39359478, 2024).
teratoma (1 paper, 2014). A non-seminomatous germ cell tumor characterized by the presence of various tissues which correspond to the different germinal layers (endoderm, mesoderm, and ectoderm). "Therefore, STAT3 could be an attractive target to control teratoma development by direct effects on ESC growth and macrophage M2-like activation." (PMID 25071759, 2014).
Theileria infection (1 paper, 2025). "Theileria infection normally triggers cytokine secretion such a GM-CSF19, activating TFs (STAT3, PI3-K, AP-1, and E2F) that drive c-MYC production." (PMID 40368139, 2025).
Tinnitus (1 paper, 2022). Tinnitus is an auditory perception that can be described as the experience of sound, in the ear or in the head, in the absence of external acoustic stimulation. "The core components of Liuwei Dihuang Pill in the treatment of tinnitus including quercetin, stigmasterol, kaempferol, β-sitosterol, tetrahydroalstonine, which may act on core targets such as STAT3, transcription factor AP-1 (JUN), tumor necrosis factor (TNF), interleukin-6 and MAPK3." (PMID 36401375, 2022).
transient cerebral ischemia (1 paper, 2021). "In particular, activation of the JAK2/STAT3 signaling pathway may contribute to neuronal damage following transient cerebral ischemia in rats." (PMID 33514001, 2021).
uterine cancer (1 paper, 2018). Primary or metastatic malignant neoplasm involving the uterine corpus and/or the cervix. "STAT3 mutation mainly occurred in uterine cancer and existed in a hotspot in SH2 domain." (PMID 29423040, 2018). "In addition, STAT3 mutation mainly occurred in uterine cancer and existed in a hotspot in SH2 domain." (PMID 29423040, 2018).
uterine sarcoma (1 paper, 2023). "In addition, RACGAP1 activated the STAT3-survivin signaling pathway in uterine sarcoma and hepatocellular carcinoma." (PMID 37196108, 2023).
viral pneumonia (1 paper, 2026). Inflammation of the lung parenchyma that is caused by a viral infection. "KEGG enrichment analysis indicated that DLQGD could regulate PI3K-Akt signaling pathway, Stat3 signaling pathway and MAPK signaling pathway in viral pneumonia, which are associated with virus-induced inflammatory response." (PMID 41601832, 2026). "Through the construction of a comprehensive PPI network, we identified six core targets, including STAT3, AKT1, PIK3CA, PIK3R1, JUN, and MAPK1, which are likely central to the mechanism of action of DLQGD in viral pneumonia." (PMID 41601832, 2026). "In the setting of viral pneumonia, the PI3K-Akt signaling pathway, Stat3 signaling pathway and MAPK pathway are frequently activated by viruses such as influenza, RSV and SARS-CoV-2, promoting a hyperinflammatory state that contributes to the cytokine storm and acute lung injury." (PMID 41601832, 2026).
tumor (9,039 papers, 2002 to 2026). "Meanwhile, JAG2-Notch signaling facilitates Treg differentiation via tumor-associated neutrophils, complementing the STAT3-mediated suppression of T cell function." (PMID 41601649, 2026). "Our study demonstrates that SMAD4 loss enables NFATc1 to drive STAT3 expression, creating a dependency that fuels tumor progression." (PMID 40856537, 2026). "In this context, we describe a paracrine signalling interaction in which CAF-associated S100-A11 is linked to activation of the RAGE/STAT3 axis in tumour cells, accompanied by increased proliferation and reduced sensitivity to treatment." (PMID 42155177, 2026). "Activation of signal transducer and activator of transcription 3 (STAT3) is implicated in tumor progression and correlates with poor prognosis and reduced survival." (PMID 42194100, 2026). "In the GBM microenvironment, oncostatin M (OSM) derived from tumor‐associated macrophages (GAMs) activates STAT3 by binding to the OSMR/LIFR–GP130 receptor complex, driving mesenchymal transition of GBM cells." (PMID 41583906, 2026). "This study aimed to assess the synergistic tumor-inhibitory effects of melphalan-curcumin combined treatment and to investigate the roles of ROS, apoptosis, and STAT3-associated signaling, including validation in a three-dimensional (3D) tumor spheroid model." (PMID 42198233, 2026). "Hepatic LRG1 induced by tumor-associated inflammation via IL-6/STAT3 signaling promotes liver metastasis through the formation of TGFBR/PI3K/AKT axis-driven neutrophil extracellular traps (NETs)." (PMID 41963620, 2026). "In summary, IL-6, TNF-α, IL-17A, and CXCL8 (IL-8) emerge as the cytokines most strongly linked to promoting anoikis resistance in tumor cells, activating survival pathways like NF-κB, STAT3, and AKT/ERK." (PMID 41596231, 2026). "IL-6 activates tumor cells to induce the expression of STAT3 target genes, which in turn encode proteins that promote tumor growth (such as cyclin D1) and/or survival (such as BCL-2-like protein 1 (BCL-xL)." (PMID 41596531, 2026). "Mechanistically, OLIG2 recruited HDAC7 to repress CXCL10 transcription, inducing STAT3 activation in tumor-associated macrophages (TAMs) and decreasing CD8+ T cell infiltration and activation." (PMID 41591814, 2026). "In cancer, STAT3 activation is usually closely associated with tumor growth, invasion, and metastasis." (PMID 40872503, 2025). "The Jak2/Stat3 pathway served as a key mediator of oncogenesis and tumor angiogenesis, and its dysregulation was linked to poor prognosis in multiple cancer types." (PMID 40840329, 2025). "As a subunit of CCT, CCT3 is closely associated with the expression of tumor-related proteins, genes, and cell cycle regulatory proteins, such as cell cycle regulators and STAT3." (PMID 39928781, 2025). "The cooperative effects between GKN2 loss and STAT3 hyperactivation demonstrate the multihit nature of gastric carcinogenesis and highlight the importance of both tumor suppressor inactivation and oncogenic pathway activation in human disease." (PMID 40673273, 2025). "Two of the main pathways are NF-κB and STAT3, which can be activated by cytokines, leading to cellular gene damage and mutations, ultimately resulting in tumour development." (PMID 40407951, 2025). "FOXP3 T allele deletion and HLA‐G polymorphism in the blood of patients correlate with higher STAT3 tumor expression and elevated IL‐4 and IL‐17 blood cytokines." (PMID 41263059, 2025). "STAT3 and NF-κB share notable similarities and differences as nuclear transcription factors controlling genes implicated in tumor growth, survival, invasion, angiogenesis, metastasis, and inflammatory cytokines driving cancer." (PMID 40420174, 2025). "Secondly, elevated CCL2 levels recruit tumor-associated macrophages (TAMs), which secrete IL-6 and activate STAT3, further promoting immune modulation." (PMID 40087784, 2025).
tumor (continued). "The NF-κB and STAT3 signaling pathways have been identified as the two primary molecular cascades that regulate M2 polarization in tumor-associated macrophages." (PMID 40963562, 2025). "In breast cancer, tumor-associated macrophages (TAMs) secrete IL-11, which activates NF-κB and STAT3 to drive invasive phenotypes." (PMID 40562870, 2025). "For example, IL-6 mediated activation of the JAK/STAT3 pathway has been shown to be closely associated with enhanced immune suppression and accelerated tumor development in osteosarcoma." (PMID 40959080, 2025). "STAT3 is a well-established oncogenic signaling pathway in various types of cancers, and its sustained activation is closely associated with tumor proliferation, metastasis, and immune evasion." (PMID 40837580, 2025). "Phosphorylation of STAT3 at Tyr705 drives its translocation into the nucleus, where it regulates a spectrum of tumour-associated biological processes, including angiogenesis, migration, invasion, cell proliferation, and the maintenance of cancer cell stemness." (PMID 41463025, 2025). "For example, cytokines released by infiltrating immune cells (such as neutrophils or tumor-associated macrophages) can trigger cascades such as JAK/STAT3 and NF-κB in tumor cells, enhancing their survival and stemness program." (PMID 40806546, 2025). "It was suggested that IL-6 levels in tumour-associated endothelial cells correlate with the tumourigenicity of CSCs, as evidenced in vitro by the p-STAT3 activation, survival, and self-renewal of human CSCs." (PMID 41009413, 2025). "Lactic acid can also promote M2-like polarization of tumor-associated macrophages (TAMs) by regulating the ERK/STAT3 signaling pathway, and induce myeloid-derived suppressor cells (MDSCs) through the regulation of HIF-1α." (PMID 41236698, 2025). "The STAT3-stimulating activity of IL-6 has recently been associated with the suppression of T cell anti-tumor activities." (PMID 39652104, 2025). "High STAT3 expression was positively associated with epithelial apoptotic processes, suggesting enhanced tumor suppression through regulated cell death, and with TNF-α signaling via NFκB, indicating robust anti-tumor immunity." (PMID 40636126, 2025). "Coculturing tumor-derived MDSCs with endothelial cells has demonstrated that STAT3+tumor-associated MDSCs induce the formation of endothelial cell tubes." (PMID 41368628, 2025). "STAT3 activation has been implicated in tumor growth, immune evasion, and suppression of dendritic cell maturation, while NF-κB signaling is essential for T cell activation and antitumor immunity." (PMID 41226910, 2025). "In other studies using the AOM-DSS model, mice deficient in STAT3 in their intestinal epithelial cells demonstrated reduced tumor size and reduced tumor incidence." (PMID 41226842, 2025). "Although poly(ADP-ribose) polymerase inhibition shows efficacy in BRCA-mutated OC, it concurrently upregulates STAT3 signaling in tumor cells, inducing pro-tumor TAM polarization and ultimately driving therapy resistance." (PMID 41417432, 2025). "Tumor development due to STAT3 aberrant activation results from loss of competent immune signaling and by the induction of a pro-inflammatory response in the tumor microenvironment." (PMID 41463071, 2025). "IL6 is known to promote STAT3 activation, which has been widely implicated in cancer-induced immune tolerance and tumor progression." (PMID 41514627, 2025). "Upregulation of STAT3 in association with different cytokines was essential in regulating various processes in promoting cancer including, tumor progression, proliferation, and metastasis." (PMID 41186627, 2025). "The IL-6/JAK1/STAT3 signal axis is implicated in promoting inflammatory responses and cellular proliferation, thereby influencing the tumor microenvironment and potentially exacerbating the susceptibility to gastric carcinogenesis." (PMID 41284643, 2025).
tumor (continued). "The STAT3 (signal transducer and activator of transcription 3) protein has been implicated in the CpG methylation of tumor suppressor genes in liver, breast, and hematopoietic cancers by promoting the expression, activation, and stability of DNMTs." (PMID 40427627, 2025). "STAT-3 regulates processes associated with tumor development, such as cell cycle progression, the inhibition of apoptosis, and ECM remodeling." (PMID 40943781, 2025). "STAT-3 activation via IL-6 is associated with more aggressive tumor behavior, worse outcomes, shorter survival times, and more advanced NMIBC." (PMID 40227644, 2025). "Persistent activation of the IL-6/STAT3 pathway, for instance, has been implicated in tumor-promoting processes including angiogenesis, epithelial-to-mesenchymal transition (EMT), invasion, and immune evasion." (PMID 41479671, 2025). "Tumor cells can promote the rapid differentiation of M‐MDSCs into tumor‐associated macrophages (TAMs) by downregulating the activity of signal transducer and activator of transcription 3 (STAT3), thus facilitating immune evasion." (PMID 40452814, 2025). "In recent years, numerous reports have indicated that JAK2 and STAT3 are closely associated with various malignant behaviors in tumor cells, including cell cycle regulation and apoptosis." (PMID 41347093, 2025). "Specifically, high lactate concentrations induce K63-linked lactylation of ENSA, activating the STAT3/CCL2 signalling pathway to recruit tumour-associated macrophages and ultimately induce immunotherapy resistance." (PMID 41463025, 2025). "These cytokines have been associated with tumor-promoting inflammation, possibly through STAT3 signaling." (PMID 41375042, 2025). "For example, silibinin impedes the growth of brain metastasis by targeting STAT3 in tumor-associated astrocytes, thereby reducing their crosstalk with cancer cells and microglia." (PMID 39979279, 2025). "XH Zhou found that HCC-derived exosomes induced the overexpression of microRNA-761 (miR-761) in HCC, and reprogrammed the tumor microenvironment via targeting the SOCS2/JAK2/STAT3 pathway, which activated the tumor-associated fibroblasts (CAFs)." (PMID 41567219, 2025). "The activated STAT3 is frequently linked with tumor invasion, metastasis, and prognosis by increasing cancer cell proliferation, survival, and angiogenesis." (PMID 40350446, 2025). "To further elucidate the molecular effectors underlying the functional differences between the two tumor cell states, we focused on investigating the role of STAT3, a key regulator enriched in Spc-high/CD44-low cells." (PMID 39930268, 2025). "Previous research has shown that transferrin receptor 1 (TFR1) and STAT3 signaling are closely linked to iron metabolism and tumor immune escape." (PMID 41551164, 2025). "RES treatment led to a significant reduction in tumor growth, which was associated with the inhibition of cell proliferation and decreased expression of p‐STAT3 in tumor tissues." (PMID 40860906, 2025). "Activation of the transcription factor STAT3 also causes the production of different proteins and cytokines that regulate tumor growth, angiogenesis, metastasis, or resistance to anti-cancer therapies." (PMID 40076874, 2025). "Signal transducer and activator of transcription 3 (STAT3) is a versatile transcription factor that is intimately linked to the transformation, survival, invasion, proliferation, and metastasis of tumor cells as well as the tumor inflammatory response." (PMID 40439888, 2025). "Our data demonstrate ITGA2hi‐PTC cell‐driven polarization of tumor‐associated macrophages (TAMs) toward immunosuppressive M2 phenotypes via JAK2/STAT3 activation." (PMID 40985182, 2025). "STAT3 activation, mediated by IL-6, inhibits the activation of T lymphocytes, tumor-associated macrophages (TAMs), NK cells, and neutrophils." (PMID 41357220, 2025).